FCHO2 (FCH and mu domain containing endocytic adaptor 2)
Description:
Functions in an early step of clathrin-mediated endocytosis. Has both a membrane binding/bending activity and the ability to recruit proteins essential to the formation of functional clathrin-coated pits. Has a lipid-binding activity with a preference for membranes enriched in phosphatidylserine and phosphoinositides (Pi(4,5) biphosphate) like the plasma membrane. Its membrane-bending activity might be important for the subsequent action of clathrin and adaptors in the formation of clathrin-coated vesicles. Involved in adaptor protein complex AP-2-dependent endocytosis of the transferrin receptor, it also functions in the AP-2-independent endocytosis of the LDL receptor.
Tractability: Antibody: UniProt places it where antibodies can reach, with medium confidence; its Gene Ontology location is reachable by antibodies, with medium confidence. PROTAC: UniProt records ubiquitination sites on it; ubiquitination databases record sites on it; its protein half-life has been measured.
Gene: Protein-coding gene on chromosome 5 (72,955,988 to 73,090,522, forward strand). Ensembl gene ENSG00000157107.
Subcellular location: Membrane, clathrin-coated pit
Subcellular location (Human Protein Atlas): Centrosome; Cytosol; Vesicles
Pathways (Reactome):
Vesicle-mediated transport: Cargo recognition for clathrin-mediated endocytosis; Clathrin-mediated endocytosis
Gene Ontology:
Molecular function: protein binding; phosphatidylinositol binding; phosphatidylinositol-4,5-bisphosphate binding; phosphatidylserine binding; identical protein binding
Biological process: clathrin coat assembly; clathrin-dependent endocytosis; membrane invagination; protein localization to plasma membrane; synaptic vesicle endocytosis
Cellular component: clathrin-coated pit; clathrin-coated vesicle; cytoplasm; cytosol; plasma membrane; presynapse; synapse
Genetic constraint (gnomAD): Loss-of-function variants: 19 observed, 50.79 expected, observed/expected ratio (o/e) 0.37, 90% interval 0.26 to 0.55. The upper end of that interval is the gene's LOEUF score, 0.55, which puts it in group 2 of 6, group 1 being the genes least tolerant of losing a copy. Missense variants: 505 observed, 595.35 expected, observed/expected ratio (o/e) 0.85, 90% interval 0.79 to 0.91. Synonymous variants: 208 observed, 207.85 expected, observed/expected ratio (o/e) 1, 90% interval 0.89 to 1.12.
Homologues: Orthologues: chimpanzee FCHO2 (99% identical), dog FCHO2 (97% identical), pig FCHO2 (97% identical), guinea pig FCHO2 (95% identical), rat Fcho2 (95% identical), mouse Fcho2 (95% identical), macaque FCHO2 (94% identical), rabbit FCHO2 (93% identical), tropical clawed frog fcho2 (79% identical), zebrafish fcho2 (70% identical). Paralogues in human: FCHO1 (49% identical), SGIP1 (39% identical), PSTPIP1 (11% identical), PSTPIP2 (10% identical), GAS7 (8% identical).
Diseases named in the same sentence as FCHO2 in open-access papers:
FCHO2 is named in the same sentence as 5 diseases in open-access papers, as found by Europe PMC text mining. Sharing a sentence is not in itself a finding about the gene and the disease. The quoted sentences say what the papers report.
gastric cancer (1 paper, 2024). A primary or metastatic malignant neoplasm involving the stomach. "Similarly, 30 blood samples and tissues from gastric cancer patients were taken to analyze circ-FCH and mu domain-containing endocytic adaptor 2 (FCHO2)." (PMID 38392967, 2024).
melanoma (1 paper, 2024). A malignant, usually aggressive tumor composed of atypical, neoplastic melanocytes. "We report here that circFCHO2(hsa_circ_0002490), a circRNA encompassing exons 19 and 20 of the FCHO2 gene, exhibited a consistent overexpression in melanoma tissues." (PMID 38311675, 2024). "In contrast, the expression of FCHO2 mRNA was significantly downregulated in the melanoma cell lines." (PMID 38311675, 2024).
cancer (2 papers, 2025). A tumor composed of atypical neoplastic, often pleomorphic cells that invade other tissues. "Many operations, that is, activation of GPER and reduction of ROCK1, TAGLN2, and FCHO2 expressions, are involved in the prevention of cancer development." (PMID 40078339, 2025). "Activation of GPER and reduction in the expressions of ROCK1, TAGLN2, and FCHO2 are some of the processes modulated by punicalagin that inhibit the development of cancer." (PMID 40018013, 2025).
infection (2 papers, 2016 to 2018). The state of being infected such as from the introduction of a foreign agent such as serum, vaccine, antigenic substance or organism. "Because of the interaction with FCHO2, we wanted to determine the relative localization of Cig57 and FCHO2 during infection." (PMID 28002452, 2016). "There is a shift towards lower Coxiella replication at day 5 post infection in the FCHO2 KO cells compared to the wild-type parent HeLa cell line." (PMID 28002452, 2016). "A yeast two-hybrid screen identified FCHO2 as a binding partner of Cig57 and this interaction was confirmed during infection using immunoprecipitation experiments." (PMID 28002452, 2016). "Using siRNA, clathrin was efficiently depleted from the cells until Day 6 however silencing of FCHO2 at days 4 and 6 post infection was of poor efficiency." (PMID 28002452, 2016). "When quantified, vacuoles are significantly (P = 0.0059) smaller during infection of our FCHO2 KO cell line (73.9±3.5 μm2) than when infecting the parental HeLa cell line (251.1±32.9 μm2)." (PMID 28002452, 2016). "Indeed, over one representative experiment, we observed a greater range of CCV/cytoplasm ratios during infection of the FCHO2 KO cells." (PMID 28002452, 2016). "Importantly, this was done in the context of infection to address whether the interaction between Cig57 and FCHO2 occurs during infection." (PMID 28002452, 2016). "To examine the roles of clathrin-dependent endocytic pathway in the enhancement of EV71-infection by CPZ, we performed siRNA knockdown of the AP2M1, CLTC, DNM2 and FCHO2 (the reported crucial CME components) in A549 and RD cells and tested the viral infectivity with additional CPZ treatment." (PMID 29298696, 2018).
tumor (1 paper, 2022). "The proteomic analysis of tumor tissues identified that rho-associated coiled-coil containing protein kinase 1 (ROCK1), transgelin 2 (TAGLN2), and FCH and Mu domain containing endocytic adaptor 2 (FCHO2) levels were significantly reduced in chrysin-treated tumor tissues." (PMID 36077069, 2022).